CD4 (CD4 molecule)
Diseases named in the same sentence as CD4 in open-access papers (continued):
Sharing a sentence is not in itself a finding about the gene and the disease.
psoriasis (continued). "Moreover, the nature of the autoantigen modification, which is likely to have an impact on the “adjuvant activity” of native LL37, appears to influence the fate of the psoriasis CD4 T cells with respect to T-helper cell polarization outcomes and, likely, effector functions." (PMID 40270954, 2025). "This immunological interference could explain why latitude differences were not apparent in the present study, as the dominant influence of HIV on CD4+ lymphocytes might lead to a more uniform pattern of psoriasis prevalence across different latitudes in the HIV-infected population." (PMID 41207052, 2025). "For example, the activation of AhR in CD4+ T cells can drive differentiation toward the Th17 and Th22 subtypes, which may inadvertently trigger skin inflammation in patients suffering from AD or psoriasis." (PMID 39939818, 2025). "In this light we made the hypothesis that highly differentiated memory CD4+ and CD8+ T cells, amplified in the psoriatic plaques, can circulate and play a role in the cardiovascular comorbidities associated with psoriasis in a possible synergy with soluble inflammatory mediators." (PMID 40599782, 2025). "Thus, this suggests that CD4 plays an equally important role in psoriasis." (PMID 38558803, 2024). "Thus, TCM drugs that mainly improve the differentiation of CD4+ T cells may be the first choice for the treatment of psoriasis." (PMID 38363920, 2024). "Notably, our findings suggest that monitoring CD28 and CD127 expression levels on CD4+ TCM and CD4+ TN could be crucial in identifying psoriasis patients at high risk of developing arthritis." (PMID 38590608, 2024). "Additionally, both CISH and CLU were found upregulated in I) CD4+ TCM and CD4+ TEM and II) CD14+ monocytes, respectively, which are associated with IL-1β-induced and synovial inflammation, and increased levels have been related to psoriasis and arthritis." (PMID 40084238, 2024). "Therefore, we developed a 3D psoriasis model with integrated TH1-polarized CD4+ T cells." (PMID 38251799, 2024). "We detected very low frequencies of IL-17+ CD4+ T cells after stimulation of patient and control MNCs with LL-37 or citLL37, but citLL37 did induced a significant increase in the proportion IL-17 producing cells from patients with psoriasis compared to unstimulated and LL-37 stimulated cultures." (PMID 38173716, 2023). "The promoter of the p16INK4a gene is methylated in the epidermis of psoriasis patients, and p16INK4a mRNA expression is also elevated, with high degrees of methylation of the promoter region and hypomethylation of some other regions also occurring in CD4+ cells." (PMID 37762693, 2023). "Furthermore, CD4+T cells are important immune cells in the pathogenesis of psoriasis." (PMID 35409158, 2022). "S100A8, which is highly expressed in the lesion skin and serum of psoriasis patients, is produced by keratinocytes in the lesion skin and is thought to be involved in the pathogenesis of psoriasis via its chemotactic activity for neutrophils and CD4+ T lymphocytes." (PMID 36620087, 2022). "An explanation could be the decreased frequency of CD4+CD25high Tregs in guttate psoriasis." (PMID 35967358, 2022). "For example, CDK7 was identified by proteomics, and then its related function was proved by further experience to reveal that the downstream mechanism CDK7 could promote CD4+ T-cell activation and Th17/Th1 cell differentiation by regulating glycolysis, contributing to the pathogenesis of psoriasis." (PMID 36338621, 2022). "In addition, the decreased portion of CD4+T-positive cells indicates that ME gel could alleviate psoriasis disorders via immune regulation." (PMID 35409158, 2022). "However, an increase in CD4+ T cell activation was found in psoriasis patients." (PMID 35186952, 2021).
psoriasis (continued). "Significant differences between severe and mild–moderate psoriasis were found for median glucose (101.5 mg/dL vs. 92 mg/dL), triglycerides (135 mg/dL vs. 103 mg/dL), the percentage of patients with metabolic syndrome (45% vs. 21%), and nadir CD4+ lymphocyte count (124.5 cells/mm3 vs. 230 cells/mm3)." (PMID 34064387, 2021). "In addition, CD4+CD25+Foxp3+ Tregs could differentiate into IL-17A–producing Th17 cells in psoriasis and aggravate its symptoms by inducing imbalance of Th17/Treg, activating effecting T cells and immune response in skin." (PMID 33981308, 2021). "Expectedly, we found that the immune cell profile of psoriasis and healthy skin is dramatically different in lesional compared with non-lesional skins, including activated mast cells, activated dendritic cells, activated CD4+ memory T cells, macrophage M0, macrophage M1 and neutrophils." (PMID 34887864, 2021). "Therefore, to further determine whether CD8αα+T cells have an immunosuppressive function in psoriasis, we cocultured CD8αα+T cells with auto‐CD4+T cells." (PMID 35663772, 2021). "Specifically, CD8 T-cells; CD4+ Th17 cells, responsible for producing IL-17 and IL-22; type 3 innate lymphoid cells, responsible for producing IL-17 and IL-22; and γδ T cells, responsible for producing IL-17 and TNF- α, are implicated in the pathogenesis of psoriasis." (PMID 34884596, 2021). "BA was previously found to be able to ameliorate psoriasis-like murine skin inflammation by decreasing the number of γδ T cells and IL-17A-expressing CD4+ in psoriatic mice, and inhibiting the proliferation of T cell and IL-17A production by CD4+ T-Cells in vitro." (PMID 32842569, 2020). "Moreover, sensitization with the inflammatory agent Imiquimod (IMQ), which induces a skin inflammation with common features to psoriasis in an IL-23-dependent manner, increased the frequency of IL-23R-expressing TCRγδ cells, while inducing a small increase of the CD4+IL-23R+ subpopulation." (PMID 32203518, 2020). "Likewise, perforin+ CD4+ T cells have been observed in skin lesions from patients with psoriasis." (PMID 30915067, 2019). "Besides autoreactive T-lymphocytes, Tregs are also thought to contribute to psoriasis through ineffective control of proinflammatory cells: while CD4+CD25+FOXP3+ cells are readily detectable in the blood of psoriasis patients, they are unable to suppress Th1 effects." (PMID 31191553, 2019). "Our laboratory revealed that suppression of NRIP1 in CD4+ T cells that were isolated from psoriasis patients could downregulate the expression of RelA/p65 and decrease the secretion of IL-17, thus inhibiting the inflammation in psoriasis." (PMID 31824416, 2019). "Therefore, the suppression of IL-23 by Cal and Cal/BDP may contribute to correcting the imbalance between CD4+ Tregs and proinflammatory T17 cells in the dLNs, leading to a long-term clinical response of psoriasis." (PMID 31705000, 2019). "Thus, we evaluated whether esculetin would alleviate psoriasis through inducing CD4+Foxp3+ Tregs in vivo." (PMID 30258447, 2018). "Therefore, in our study, we have also performed logistic regression analysis which has shown that estimated odds of psoriasis decreased by 36.9% if CD4+PD-1+ T cells increased by 1% and by 29.5% if CD8+PD-1+ T cells increased by 1%, compared to the control group." (PMID 29180838, 2017). "In the CD4 compartment, we found that CCR6+ CD4+ TEM cells correlated with systemic inflammation measured as serum level of C-reactive protein (unpublished data), in line with the increase of IL-17A in serum of patients with severe psoriasis and with its association with cardiovascular diseases." (PMID 27595115, 2016). "Similar studies of MSCs in psoriasis have reported increased frequencies of Tregs and CD4+ and CD8+ central memory T cells alongside a decrease in circulating Th17 and CD4+ naïve T cells." (PMID 40969757, 2025).
psoriasis (continued). "In our in vitro model systems of CD4 T-cell polarization presented here, we used recombinant IFN-α to mimic the effect of pDCs in vitro, as IFN-α was shown in the past to be crucial for psoriasis plaque formation." (PMID 40270954, 2025). "Psoriatic HaCaTs deliver AGAP2-AS1 to CD4+ T cells via exosomes, inducing Th1 and Th17 differentiation through the miR-424-5p/SGK1 axis, thereby promoting the progression of psoriasis." (PMID 40520230, 2025). "We next compared different CD4+ and CD8+ memory T cell profiles between control (n=13) and recurrent psoriasis-like (n=10) conditions." (PMID 40599782, 2025). "Together these results indicate a marked reduction in naïve CD4+ and CD8+ T cells in the psoriasis-like condition and an increase in CD8+ TCM and CD4+ TEM." (PMID 40599782, 2025). "Recurrent psoriasis-like condition in mice also induced increased activation of memory T cells, augmented frequencies of CXCR3+4-1BB+ and PD-1+TIM-3+ CD4+ T cells as well as CD8+ T cells with a highly differentiated phenotype." (PMID 40599782, 2025). "Another 2025 study comparing erythrodermic CTCL to chronic idiopathic erythroderma, atopic dermatitis, psoriasis, and healthy controls found that erythrodermic CTCL had expanded CD4+ malignant cells with a CCR7+SELL+ central memory phenotype." (PMID 40941016, 2025). "By integrating single-cell RNA sequencing with MR analysis, we identified seven psoriasis-related genes (BIN2, CAPN12, CXXC5, KLRC1, KLRD1, PRF1, and SLFN5) that are highly expressed in CD4+ T cells." (PMID 41328434, 2025). "Psoriasis was traditionally viewed as a Th1-mediated disorder, largely due to elevated IFN-γ production by CD4+ T cells within psoriatic lesions and minimal expression of Th2-associated cytokines such as IL-4, IL-5, and IL-13." (PMID 41226338, 2025). "In psoriasis, SLC3A2 was enriched in epidermal cells and exhibited strong positive correlations with T follicular helper cells and CD4+ memory T cells, two immune subsets central to psoriatic inflammation." (PMID 41224720, 2025). "As MAIT cells display an EM-like phenotype, a similar correlation between circulating CXCR3+CD4+ EM T cells and PASI scores was observed in patients with psoriasis." (PMID 40391222, 2025). "In contrast, the proportions of Sema4A-positive cells were significantly higher in blood CD4 and CD8 T cells, and monocytes in psoriasis compared to Ctl." (PMID 39737847, 2024). "The coffee intervention group showed a lower frequency of CD4+ and CD8+ effector T cells and a greater frequency of Treg cells in IMQ‐induced psoriasis‐like mice." (PMID 38887468, 2024). "HER4 is also expressed in CD4+ T cells from patients with psoriasis, and treatment with HER4 siRNA reduced mouse IL-17A+ CD4+ T cells in vitro and imiquimod-induced dermatitis in vivo." (PMID 38312837, 2024). "Forkhead box protein-3 (FOXP3) is a marker of regulatory T cells (Tregs), especially CD4+ Tregs, however, FOXP3 is also expressed in CD8+ T cells and FOXP3 expression is increased in psoriasis lesions." (PMID 38915827, 2024). "Interestingly, CD4 cells with cytotoxic activity have been identified in several skin diseases, such as diabetic ulcers, dermatitis, and psoriasis, suggesting that they may mediate pathogenesis through mechanisms similar to those described in this work, which warrants further investigation." (PMID 39497830, 2024). "In this study, we thoroughly analyzed psoriasis and AD skin models induced by cytokine stimulation or by integrated TH1 CD4+ T cells for histology and function." (PMID 38251799, 2024). "Conversely, two traits showed protective connections with psoriasis: CD28 on CD39+ activated Treg (IVW: OR 0.9995, 95% CI 0.9990–1.0000; p = 3.250596e−02), CD25 on CD39+ CD4 Treg (IVW: OR 0.9984, 95% CI 0.9973–0.9995; p = 3.969029e−03)." (PMID 38558803, 2024).
psoriasis (continued). "Tissue-resident memory T (TRM) cells also contribute significantly to the pathogenesis and recurrence of psoriasis, as the sustained presence of IL-17-secreting CD8+ T cells and IL-22-secreting CD4+ T cells can result in chronic inflammatory plaque formation." (PMID 38596682, 2024). "Flow cytometry also revealed increased populations of CD4+EBI3+p35+ and CD19+EBI3+p35+ cells in the peripheral blood of patients with psoriasis." (PMID 36969174, 2023). "CD4 and CD8 T-cell infiltrate characterizes the skin in psoriasis, a T-cell-driven disease, but other cell types are also present in the lesions, including neutrophils, macrophages, NK cells, dendritic cells." (PMID 36901778, 2023). "A similar approach is used in keratinocytes from patients with psoriasis, where deleting LAT1 controls skin inflammation, while CD4+ T cells use alternative amino acid transporters (LAT2 and LAT3)." (PMID 37274280, 2023). "The recruitment and activation of CD4+, CD8+ T cells, Th17 cells, innate lymphoid cells (ILCs), and γδ T cells subsequently trigger KCs in psoriasis humoral immune response and inflammatory response." (PMID 38239345, 2023). "Both helper CD4+ and cytotoxic CD8+ TRM have been found in the skin and also act as responders in autoimmunity as well as in psoriasis and other skin diseases." (PMID 37958689, 2023). "Serum CD147 levels were increased in psoriasis patients and the CD147 and MCT-1 expressions were elevated on their CD4+ RORγt+ Th17 cells in the dermis." (PMID 38139173, 2023). "To characterize T17 cell transcriptome in psoriasis skin, we segregated T-cell (CD161+ T-cell, CD8+ T-cell, CD4+ T-cell, and Treg) clusters in the scRNA-seq data and tested if psoriasis T-cells express more T17 cell genes than control T-cells." (PMID 37781383, 2023). "CDK7 expression was markedly increased in CD4+ T cells from patients with psoriasis, and its inhibitor THZ1 ameliorated psoriasiform symptoms in an imiquimod-induced psoriasis-like mouse model." (PMID 37762693, 2023). "In this investigation, we described single-cell transcriptomic landscape of immunometabolism reprogramming in circulating Tregs, CD4+ TCMs and CD8+ TEMs subsets of psoriasis and psoriatic arthritis." (PMID 37492568, 2023). "The AIM2 total fluorescence intensity in CD4+ Trm cells in patients with SCLE and localized DLE were higher than in patients with psoriasis." (PMID 36118867, 2022). "Then splenic CD4+ T cells were obtained to assess the in vivo effect of IFNγ-sEVs and ASO-210 on the immune imbalance of Th cell subsets in a psoriasis-like IMQ mouse model." (PMID 35359454, 2022). "Dermal dendrocytes of monocytic origin that express CD4, LFA-1, and Factor XIIIa are the main HIV-infected cells in patients with psoriasis." (PMID 35805960, 2022). "Increased CD3+CD4+CXCR3+, CD3+CD4+CCR6+CCR4+CXCR3+(CXCR3+-Th17), and CD3+CD4+CCR6+CCR4-CXCR3+(Th17.1) cell populations were observed in patients with psoriasis in comparison to healthy individuals (n = 10)." (PMID 35925616, 2022). "In line, single-cell RNASeq analysis of psoriasis also indicated few transcripts per IFNG or IL17A transcript-positive cells, with a median UMI count for IFNG or IL17A of 1 per CD4+ cell and 4 per CD8+ cell." (PMID 36513651, 2022). "When the profile of CD4+ T cell subsets in the spleen and draining lymph node (dLN) of the psoriasis animal model was examined, the high level of T-bet+ or IFN-γ+ CD4+ T cells and ROR-γt+ or IL-17A+ CD4+ T cells was detected in psoriasis-induced mice." (PMID 36591260, 2022). "The pathogenesis of psoriasis is characterized by a complex interplay between IL-17 and IFN-y producing CD4+ and CD8+ T-cell subsets." (PMID 35967358, 2022). "For instance, the NF-κB pathway activates Th17 differentiation to involve in psoriasis development; the JNK pathway promotes CD4+ T cell infiltration in Sjogren’s syndrome." (PMID 35967391, 2022).
psoriasis (continued). "During the early onset of psoriasis, DCs release TNF-α along with other cytokines, such as IL-23, to signal for the assembling of CD4+ and CD8+ T cells." (PMID 35203707, 2022). "Sigmundsdóttir, in psoriasis study, reported that CD3 + CD8 + CLA + cells were more related to the disease severity than CD3 + CD4 + CLA + cells." (PMID 36397025, 2022). "The expression of CD4-positive lymphocytes, as well as CD8-positive lymphocytes and macrophages, were found to be significantly increased in the psoriasis patients' skin epidermis and dermis in comparison with healthy skin." (PMID 33936220, 2021). "Recent studies have shown that in addition to CD4+T cells, γδT cells, dendritic cells, neutrophils and CD8+T cells are also found to produce pro‐inflammatory factors in patients with psoriasis." (PMID 35663772, 2021). "While IL-17A-producing CD4+ TRM also exist in healthy skin, the enrichment of CD8+ TRM producing IL-17A in the epidermis is one of the characteristics of psoriasis." (PMID 34501272, 2021). "Based on immune chemistry, the levels of CD2+, CD4+, CD8+ T-lymphocytes were also found to be raised in both depression and psoriasis, validating their relationship." (PMID 34183985, 2021). "In the lesional skin of patients with psoriasis, TRM consist of both CD4 and CD8 fractions, which synchronize the elevated immune response by the increased expression of inflammatory cytokines, such as IL-17A, IL-22, and IFN-γ." (PMID 34501272, 2021). "Both CD4+ (regulatory, helper) T cells and CD8+ (effector, cytotoxic) T cells play an important role in the development of psoriasis." (PMID 34371756, 2021). "These CD4+CD146+ T cells were also shown in psoriatic skin lesions and these cells were also producing IL-17 implicating their role in psoriasis in which IL-17 plays a significant role." (PMID 34491483, 2021). "The percentages of CD4+ and CD8+ T cells in the PBMCs were comparable between psoriasis patients and healthy controls." (PMID 35186952, 2021). "Further, another study reported that the peripheral blood levels of PD-1-positive CD4+ T cells and CD8+ T cells in the psoriasis group were markedly lower than those in the healthy control group." (PMID 34768720, 2021). "In our group of 32 psoriasis patients, there was statistically significant increase in the immunoreactive area of CD8 in the epidermis, CD4 in the dermis and, to a lesser extent, in the epidermis compared to the control group." (PMID 34769769, 2021). "Moreover, among them, IL-17, which is mainly produced by γδ T cells, CD4+ helper T cells (Th17 cells), and CD8+ cytotoxic T cells (Tc17 cells), seems to be most strongly implicated in psoriasis; thus, T cells, especially helper T (Th) cells, have become a hot topic in psoriasis pathogenesis." (PMID 34975883, 2021). "The pan-HDAC inhibitor trichostatin A acts on human peripheral blood-derived CD4+CD25+Foxp3+ Tregs, reversing their conversion into Th17 cells and increasing Foxp3 expression in healthy controls and in patients with psoriasis." (PMID 34501328, 2021). "The serum level of CD147 was increased in patients with psoriasis, and the expression of CD147 and MCT-1 was elevated in their dermal CD4+ RORγt+ T cells." (PMID 35008603, 2021). "Regulatory CD4+CD25+ T-cells (Tregs), which maintain immune tolerance by secreting inhibitory cytokines and inducing apoptosis, are damaged in psoriasis and cannot suppress the proliferation of effector T lymphocytes." (PMID 34769005, 2021). "Other subpopulations of Th lymphocytes, such as Th9 and follicular CD3+CD4+CXCR5+ T lymphocytes, also contribute to the pathogenesis of psoriasis, most likely by potentiation of existing immune events, especially the IL-17 pathway." (PMID 34769005, 2021). "While CD3+CD4+ T cells proliferated in response to LL37 and cit-LL37 in both SLE and psoriasis, only in SLE a substantial humoral anti-LL37/cit-LL37 response developed, suggestive of a preferential expansion of TFH in SLE." (PMID 32245990, 2020).